CDK1 (cyclin dependent kinase 1)
Diseases named in the same sentence as CDK1 in open-access papers (continued):
Sharing a sentence is not in itself a finding about the gene and the disease.
melanoma (continued). "Further studies presented that ZBSO could constrain CDC25A/CyclinB1/CDK1 signaling pathway in vitro and in vivo models of melanoma." (PMID 37081962, 2023). "CDK1 orchestrates a dual mechanism by directly engaging with the pivotal cancer stemness-related protein Sox2 to drive tumor initiation in melanoma, while simultaneously preserving tumor stemness characteristics and pluripotency through phosphorylating TFCP2L1 in human bladder cancer." (PMID 37743465, 2023). "On the other hand, proliferation-related genes, including cdk2, minichromosome maintenance complex component 7 (mcm7), pcna, marker of proliferation Ki-67 (mki67), and cdk1 were upregulated in the melanoma tissues while being unaltered in nevi, when compared to the control." (PMID 38020918, 2023). "CDK1 promoted tumor initiation in human melanoma through interacting with Sox230." (PMID 35906389, 2022). "In our study, the expression of CDK1 was downregulated in shCCT3 melanoma cells." (PMID 35399722, 2022). "We speculate that CDK1 is involved in the process of melanoma metastasis by regulating the function of the tumor microenvironment." (PMID 35906389, 2022). "Then, these results may imply that CCT3 silencing regulates the expression of CDK1, and affects the process of the cell cycle, resulting in the inhibition of proliferation of melanoma cells." (PMID 35399722, 2022). "CDK1 can serve as a potential downstream target of CCT3 in melanoma." (PMID 35399722, 2022). "In summary, 294 DEGs between the primary and metastatic skin cutaneous melanoma samples were screened, and four hub genes, CDK1, FOXM1, KIF11, and RFC4, were identified that may be associated with the metastasis of melanoma." (PMID 35906389, 2022). "The upregulation of CDK1 can promote the growth and the proliferation of melanoma tumor cells." (PMID 36193491, 2022). "CDK1 was identified as a hub gene involved in the progression of melanoma metastasis and may be regarded as a therapeutic target for melanoma patients to improve prognosis and prevent metastasis in the future." (PMID 35906389, 2022). "Notably, accumulating evidence suggests that cAMP signaling can strongly suppress the activity of CDK1 mainly owing to the phosphorylation of Cdc25B and subsequent phosphorylation of CDK1 in various cell types, including melanoma cells." (PMID 33171851, 2020). "Further, the interaction between CDK1 and Sox2 promotes tumor initiation in human melanoma." (PMID 30841635, 2019). "Strikingly, overexpression of LINC-PINT significantly reduced melanoma cells progression via downregulating the potential target genes CDK1, CCNA2, AURKA, and PCNA through recruiting EZH2 protein, which in turn mediated the trimethylation of H3K27 of promoter regions of target genes." (PMID 31921860, 2019). "Interestingly, CDK1 overexpression or elevated cyclin B expression is often observed in human cancers especially in melanoma." (PMID 26440309, 2015). "Furthermore, inhibition of BRAF with vemurafenib, or MEK with UO126, potentiated effects of Nutlin3 and cyclin B /CDK1 inhibition, inducing apoptosis of melanoma in vitro and in vivo." (PMID 24743024, 2014).
melanoma (continued). "Consequently, the downregulation of PCNA protein and the CDC25A/CyclinB1/CDK1 pathway may be the mechanism of ZBSO against melanoma." (PMID 37081962, 2023). "Moreover, CHPF can promote the tumorigenicity of malignant melanoma by regulating CDK1." (PMID 33809195, 2021). "In human melanoma, the interaction between CDK1 and SOX2 could promote tumorigenesis." (PMID 33178832, 2020). "A series of paracyclophanyl–thiazole hybrids incorporating a naphthoquinone scaffold was designed and synthesized as potential cyclin-dependent kinase 1 (CDK1) inhibitors, exhibiting pronounced antiproliferative activity against melanoma cells." (PMID 41471376, 2025). "Given the dual oncogenic role of CCNB1 in resisting NK cell-mediated killing and enhancing melanoma invasiveness, we propose that CCNB1/CDK1 inhibitors represent a promising strategy to enhance NK cell-based immunotherapy for melanoma." (PMID 40430484, 2025). "Mechanistically, in melanoma cells, the CCNB1/CDK1 complex phosphorylates STAT3, activating the IL-6/STAT3 positive feedback loop, which upregulates PD-L1 and enables resistance to NK cell-mediated cytotoxicity." (PMID 40430484, 2025). "The results suggested that melanoma patients with high expression of CDK and FOXM1 had shorter OS (CDK1: OS P = 0.047; FOXM1: OS P = 0.00043)." (PMID 35906389, 2022). "PHA-793887 is an inhibitor of multiple cyclin-dependent kinases (CDKs), with activity against CDK2, CDK1, and CDK4, and has been validated to enhance immunotherapy against melanoma." (PMID 35680563, 2022). "The results showed that three hub genes (CDK1, KIF11 and RFC4) were significantly upregulated in metastatic melanoma tissues compared in primary melanoma tissues." (PMID 35906389, 2022). "In melanoma, the downstream kinase targets of CBX7 are Polo-like kinase 1(PLK1) and cyclin-dependent kinase 1(CDK1), which are related to genome stability." (PMID 34659360, 2021). "To examine the function of p75NTR‐FL/CTF in melanoma, we quantified the mRNA levels of cell‐cycle effectors, including cyclin‐dependent kinase 2 (CDK2), CDK4, cyclin D1, cyclin B1 and cyclin‐dependent kinase 1 (cdc2), by quantitative RT‐PCR (qRT‐PCR)." (PMID 33247998, 2021). "For instance, dinaciclib is an inhibitor of CDK1, CDK2, CDK5, and CDK9, and is active in a broad range of cancer cell lines originating from leukemia, melanoma, osteosarcoma and pancreatic cancer." (PMID 31446060, 2019). "Apart from directly targeting Cdc25 and thereby activating Cdk1, active RSK signalling can moreover weaken the G2 DNA damage checkpoint in malignant melanoma by inhibitory phosphorylation of its central checkpoint kinase Chk1." (PMID 28415756, 2017). "Downregulation of BUB1B, CDK1 and DEK provides a mechanistic explanation for the aberrant spindles and defects in cytokinesis observed after sustained depletion of CPEB4 in melanoma cells." (PMID 27857118, 2016). "RO-3306, a CCNB1/CDK1 inhibitor, can simultaneously inhibit the activity of both CCNB1 and CDK1, and has previously been shown to suppress tumor-initiating capacity in melanoma by disrupting CDK1-Sox2 signaling." (PMID 40430484, 2025). "CDK1, or cyclin-dependent kinase, is involved in the control of cell proliferation and cycle, and similar to CDK2, overexpression of CDK1 has been revealed in multiple malignancies, such as metastatic-melanoma." (PMID 39820173, 2025).
melanoma (continued). "In melanoma, CDK1 collaborates with Sox2 to promote tumor initiation, while in gastrointestinal stromal tumors, CDK1 emerges as a novel vulnerability independent of the cell cycle, offering potential therapeutic avenues for advanced-stage patients." (PMID 40746552, 2025). "The results suggested that CDK1 and FOXM1 may serve as favorable predictive factors for melanoma patient survival." (PMID 35906389, 2022). "MTT assay also showed that decreased cell proliferation due to CCT3 silencing was rescued by CDK1 overexpression (P < 0.001), suggesting that CDK1 may serve as a downstream effect of CCT3 on tumor cell growth in melanoma." (PMID 35399722, 2022). "Likewise, Icariside II increased the percentage of A375 human melanoma cells at the G0/G1 boundary with downregulations of cyclin E, cyclin B1, CDK2, and phosphorylated-CDK1 (p-CDK1)." (PMID 33981241, 2021). "Additionally, elements of several signaling pathways such as the Ras-ERK, PI3K/JNK/PKA, p27Kip1/CDK1/survivin, MAPK, HIF-1, epithelial–mesenchymal transition, and cancer stem cell pathways were also modified by treatment of xenografted melanoma mice with CDPs." (PMID 32793477, 2020). "For example, CDK1 was reported to interact with Sox2 and promote tumor initiation in human melanoma, CCNA2 and AURKA inhibitors are now available and has shown encouraging effect for treatment of melanoma." (PMID 31921860, 2019). "Furthermore, we have validated the clinical significance of our findings by unveiling the involvement of CDK1 in MYC target genes, mTOR signaling and DNA repair pathways in patient tumors from melanoma, colon and pancreatic cancer." (PMID 31080551, 2019). "Thus, one important regulator of CDK1/cyclin B1 complex, CDC25C, is suggested to be a potential oncotarget for melanoma." (PMID 30745871, 2019). "Furthermore, the expression levels of CCNA2, CCNB1, CDK1, and CDK4 decreased in melanoma cells treated with metformin, whereas the levels of p21 and CCND1 increased." (PMID 30754729, 2019). "A previous PPI network analyses conducted in a whole gene expression dataset of 31 primary melanomas and 52 metastases reported a PPI network in which PCNA, CDK1, MAD2L1, RFC4 and BRCA1 genes showed highest degree centrality values among upregulated genes in metastases." (PMID 28030792, 2017). "Furthermore, additional RNA-immunoprecipitations demonstrated binding of CPEB4 to the 3′-UTR of BUB1B, CDK1 and DEK mRNAs in melanoma cells." (PMID 27857118, 2016). "However, only CDK1 was selected for this research, whether the other four genes in WB verification were functionally regulated by CCT3 in melanoma cells needs further and in-depth study." (PMID 35399722, 2022). "The role of CDK1 in melanoma metastasis has not been reported previously." (PMID 35906389, 2022). "Although it is reported that SOX2 may start the tumor initiation process via CDK1 in melanoma, knocking-out of SOX2 by CRISPR-Cas9 does not affect melanoma progression and metastasis." (PMID 34768751, 2021). "Moreover, YTHDF1 or HNRNPA2B1 might interact with RNA processing-related genes such as CDK1/CDK2 and further promote the formation and progression of melanoma." (PMID 32549786, 2020). "Therefore, we speculated crosstalk between CDK1 and SOX2/MYC in melanoma, and silenced SOX2 in human melanoma cells." (PMID 31080551, 2019).
melanoma (continued). "Furthermore, we verified key gene expression with mRNA levels after treatment with VB1 in melanoma cells, which indicated that the P21, PUMA and GADD45A expression was significantly upregulated and that the expression of MCM6, CDK1, CDK6, CYCE and CYCA was significantly downregulated." (PMID 30400954, 2018).
colon carcinoma (75 papers, 2010 to 2025). "Previous reports on association of NOSTRIN with Cdk1/cdc2 leading to inhibition of cell cycle progression prompted our investigation on effect of NOSTRIN in regulating stemness of colon cancer cells using colonosphere formation assay." (PMID 35642021, 2022). "Curcumin inhibited the gene expression of Cdc25c, CDK1, and cyclin B1 and promoted the gene expression of Wee1 in colon cancer cells, causing cell cycle arrest at the G2/M phase." (PMID 33233354, 2020). "In a recent study, CDK1 is reported as a synthetic lethality target for KRAS mutation in colon cancer." (PMID 28486948, 2017). "A high specific activity of Cdk1 measured on 254 fresh-frozen tumor samples from stage II colon cancer patients was associated with short distant-metastasis-free intervals and poor prognosis." (PMID 25511643, 2014). "Our results demonstrate that the SA of CDK1 identifies stage II colon cancer patients with a high risk of distant disease recurrence." (PMID 22108518, 2012). "Furthermore, pseudoguaianolide (a 5/7 bicyclic compound) SLs of 6-O-angeloylplenolin, coronopilin, pulchelloid A and hymenoratin caused G2/M-phase arrest by activating cyclin B1-Cdk1/p-Cdk1 in multiple myeloma, leukemia and colon cancer cells, respectively." (PMID 35056723, 2022). "Likewise, a previous study reported that casticin, a flavonoid extracted from Achillea millefolium, caused G2/M arrest in HCT116 colon cancer cells, which was confirmed by the induction of p21 and down-regulation of CDK1." (PMID 32235558, 2020). "Specific activity of CDK1 is a promising biomarker for metastasis risk in stage II colon cancer." (PMID 22108518, 2012). "In addition, CDK1 was a promising biomarker for metastasis risk in colon cancer." (PMID 35193513, 2022). "This pro-inflammatory microenvironment is a key contributor to cancer development.The NFE2L3 transcription factor bridges NF-κB signaling to CDK1 activation, promoting the proliferation of colon cancer cells." (PMID 40595862, 2025). "Its overexpression of RAN is related to poor clinical outcomes in patients with CRC 33, and CDK1 has been identified as a potential indicator of tumor recurrence in stage II colon cancer." (PMID 38356712, 2024). "For instance, the knockdown of RPS9 in HT29 colon cancer cells induces growth inhibition and cell cycle arrest at the G2/M phase by downregulating the cell cycle regulator CDK1." (PMID 38542474, 2024). "This study revealed that remimazolam promoted the cell-cycle progression and proliferation of HCT8 colon cancer cells by upregulating CDK1, PTTG1, CDC25C, CDK4, PLK1, PCNA, Ki67, RNASEH2B, FEN1, Cyclin D1,CD44 CDK2, CDKN3, CDC45, IQGAP3, and CDK6." (PMID 38725628, 2024). "The changes in CDK1 in different grades of colon cancer tissues were also statistically significant (Pr ( > F) = 0.014)." (PMID 38134110, 2023). "CDK1 expression in different graded colon cancer tissues was also statistically significant (Pr ( > F) = 0.014)." (PMID 38134110, 2023). "In agreement to this, DPP3 was shown to be involved in cell cycle regulation and promoting malignant properties in colon cancer cells by involving CDK1." (PMID 37531267, 2023). "It has also been noted that 600 μM indomethacin significantly reduces the CDK1 levels in colon cancer cells." (PMID 37759783, 2023). "GA inhibits the activity of cdK1 enzyme in vitro and has a highly inhibitory effect on the cell proliferation of three different colon cancer cell lines (HcT-116, HT-29 and Mda-MB-231)." (PMID 35972924, 2022).
colon carcinoma (continued). "STIL knockout showed different blockade phases in different tumor types, and reduced the proliferation of cervical and colon cancer cells by inhibiting Cyclin B1/CDK1, which, in turn, induced cell cycle arrest in the G2/M phase." (PMID 36497260, 2022). "Physical interaction of NOSTRIN with Cdk1 was therefore, tested in colon cancer cells using immunoprecipitation with anti-Cdk1 (Cdc2) antibody followed by western blotting using anti-NOSTRIN antibody." (PMID 35642021, 2022). "In fact, KCTD12 interacts with CDK1 and CDC25B, forming a complex that supports CDK1 phosphorylation and cell cycle progression, while pharmacological inhibition of KCTD12-CDK1 interaction suppresses growth of colon cancer cells in vitro and in vivo." (PMID 34001146, 2021). "Cur markedly decreases CDK1 in human glioma cells and downregulates CDK1 and cyclin B1 in human colon cancer Colo 205 cells." (PMID 34572508, 2021). "After careful bioinformatic analysis of 3 GEO database and TCGA database in colon cancer, we found that miR-490-3p was significantly down-regulated and CDK1 was significantly up-regulated." (PMID 33898511, 2021). "Research also demonstrated that NFE2L3 functions as a critical regulator in a pathway that links NF-κB signaling to control CDK1 activity, thereby driving colon cancer cell proliferation." (PMID 35211477, 2021). "Data from GEO and TCGA suggested that colon cancer cells had lower miR-490-3p level and higher CDK1 level than normal colon mucosa cells." (PMID 33898511, 2021). "SFN also induced a G2/M phase arrest in colon cancer cells, accompanied by an elevation of cyclin A, cyclin B, and Cdk2, but decreased Cdk1 protein expression." (PMID 33218199, 2020). "Other investigators, however, have observed an SFN-induced up-regulation of Cdk1 in colon cancer-derived tumors." (PMID 33218199, 2020). "As a step in this direction, here we show that glucocorticoid-GR signaling plays an important role in proliferation of metastatic human colon carcinoma cells, at least in part, by inducing CDK1 gene expression." (PMID 31375708, 2019). "Depletion of GR suppressed proliferation of metastatic colon carcinoma cells and depletion of CDK1 had similar suppressing effects on proliferation as well as invasion of metastatic cells." (PMID 31375708, 2019). "Earlier reports have shown that the Hsp90 inhibitor 17-AAG can suppress CKS1, CDK1 expression, promote p27kip1 expression and lead to G1-phase arrest in colon cancer cells." (PMID 31708688, 2019). "In contrast, Hsp90, CKS1 and CDK1 had higher expression level in colon cancer tissues than in the corresponding adjacent tissues." (PMID 31708688, 2019). "First, we found that NSC 95397 does not reduce the protein level of Cdc25A and the dephosphorylation of downstream protein Cdk1 in colon cancer cells." (PMID 29857489, 2018). "Similar to treatment with apigenin, knockdown of RPS9 inhibited the growth of human colon cancer cells at the G2/M phase by downregulating cyclin-dependent kinase 1 (CDK1) expression at the promoter level." (PMID 24009741, 2013). "This study is the first report demonstrating the SA of CDK1 (CKD1SA) as prognostic biomarker for stage II colon cancer in a blinded and retrospective manner." (PMID 22108518, 2012).